EPOP (elongin BC and polycomb repressive complex 2 associated protein)
Description:
Scaffold protein that serves as a bridging partner between the PRC2/EZH2 complex and the elongin BC complex: required to fine-tune the transcriptional status of Polycomb group (PcG) target genes in embryonic stem cells (ESCs). Plays a key role in genomic regions that display both active and repressive chromatin properties in pluripotent stem cells by sustaining low level expression at PcG target genes: acts by recruiting the elongin BC complex, thereby restricting excessive activity of the PRC2/EZH2 complex. Interaction with USP7 promotes deubiquitination of H2B at promoter sites. Acts as a regulator of neuronal differentiation.
Synonyms: C17orf96; PRR28; LOC100170841
Tractability: No criterion of Open Targets' tractability assessment is met for any kind of drug.
Gene: Protein-coding gene on chromosome 17 (38,671,703 to 38,674,957, reverse strand). Ensembl gene ENSG00000273604.
Subcellular location: Nucleus; Chromosome
Subcellular location (Human Protein Atlas): Nucleoplasm; Cytoplasmic bodies; Cytosol
Pathways (Reactome):
Gene expression (Transcription): PRC2 methylates histones and DNA
Gene Ontology:
Molecular function: chromatin binding; protein-containing complex binding
Biological process: heterochromatin formation; negative regulation of transcription by RNA polymerase II; neuron fate commitment; regulation of transcription by RNA polymerase II; stem cell differentiation; transcription elongation-coupled chromatin remodeling
Cellular component: nucleoplasm; chromosome; ESC/E(Z) complex; nucleus; elongin complex
Genetic constraint (gnomAD): Loss-of-function variants: 14 observed, 10.08 expected, observed/expected ratio (o/e) 1.39, 90% interval 0.9 to 1.9. The synonymous counts are far from expectation, so gnomAD's model fits this gene poorly and the ratio says little. Missense variants: 524 observed, 406.44 expected, observed/expected ratio (o/e) 1.29, 90% interval 1.2 to 1.39. Synonymous variants: 250 observed, 188.09 expected, observed/expected ratio (o/e) 1.33, 90% interval 1.2 to 1.48.
Homologues: Orthologues: chimpanzee EPOP (99% identical), macaque EPOP (96% identical), pig EPOP (84% identical), dog EPOP (83% identical), rat Epop (75% identical), mouse Epop (74% identical), guinea pig EPOP (51% identical). Paralogues in human: SKIDA1 (26% identical), SIMC1 (12% identical).
Diseases named in the same sentence as EPOP in open-access papers:
EPOP is named in the same sentence as 6 diseases in open-access papers, as found by Europe PMC text mining. Sharing a sentence is not in itself a finding about the gene and the disease. The quoted sentences say what the papers report.
breast tumor (1 paper, 2022). "The negative correlation between CTR9 and PRC2.1 facultative subunits (PHF1/MTF2/PHF19 and EPOP) at the mRNA level was also observed in 817 ER-positive primary breast tumor samples in TCGA." (PMID 35137163, 2022).
colon cancer (1 paper, 2025). "They further demonstrated that EPOP expression in colon cancer is positively correlated with proliferation characteristics." (PMID 41425595, 2025).
colorectal cancer (1 paper, 2025). A primary or metastatic malignant neoplasm that affects the colon or rectum. "In addition, we conducted independent IHC experiments for three genes—EPOP, WDR72, and SHH—which have rarely been validated by immunohistochemistry in previous studies of colorectal cancer." (PMID 41425595, 2025).
thyroid tumours (1 paper, 2020). "EPOP A350V/P mutations, which have been observed in lung and thyroid tumours, reside in the C-terminal region of EPOP, which is essential for its binding to PRC2." (PMID 31708574, 2020).
cancer (3 papers, 2020 to 2025). A tumor composed of atypical neoplastic, often pleomorphic cells that invade other tissues. "Mutation of a crucial leucine residue (L40) in this motif impairs the association of ELOBC with EPOP and PRC2.28,29 The interaction of EPOP with ELOBC is crucial for proliferation of several human cancer cell lines." (PMID 31708574, 2020). "EPOP, Elongin B, and Elongin C are often upregulated in cancer and systematic CRISPR screening experiments demonstrated that they are “common essential” in human cancer cell lines, meaning that they are required for efficient proliferation in most human cancer cells." (PMID 35193659, 2022). "However, the function of Elongin BC towards EPOP and PRC2 as well as the reasons why EPOP and Elongin BC are required for cancer cell growth are currently unknown." (PMID 35193659, 2022). "This phenotype is dependent on EPOP interaction with ELOBC as only the wild-type version of the EPOP protein (but not the L40 mutant) is able to rescue cancer cells proliferation." (PMID 31708574, 2020).
tumor (2 papers, 2023 to 2025). "The results revealed differential expression of SHH, WDR72, and EPOP between tumor and adjacent normal tissues (P < 0.05), which aligned with our expected findings." (PMID 41425595, 2025). "Finally, immunohistochemistry (IHC) experiments confirmed the differential expression patterns of the SHH, WDR72, and EPOP genes between tumor and normal tissues, corroborating our findings at the mRNA level." (PMID 41425595, 2025). "Our independent IHC experiments further confirmed that the IHC scores of SHH (4.56 ± 1.46 vs. 2.16 ± 0.79, p < 0.0001), EPOP (4.91 ± 1.76 vs. 2.84 ± 1.05, p < 0.0001), and WDR72 (4.73 ± 2.03 vs. 2.91 ± 2.15, p < 0.01) were significantly greater in tumor tissues than in normal tissues." (PMID 41425595, 2025).